KRAS (KRas proto-oncogene, GTPase)
Diseases named in the same sentence as KRAS in open-access papers (continued):
Sharing a sentence is not in itself a finding about the gene and the disease.
tumor (continued). "Tested in vivo, ARS-1620 induced significant tumor growth inhibition and regression selectively with KRAS G12C-mutated xenografts with no response in G12V-mutated xenografts." (PMID 37190303, 2023). "These clinical investigations provide solid evidence that TCR-T cells targeting tumor-intrinsic KRAS mutants could be a promising strategy for the treatment of solid tumors." (PMID 37828002, 2023). "Additionally, they demonstrated that selectively inhibiting the HBP enzyme GFPT2 led to reduced growth of KRAS/LKB1 co-mutant tumor cells in culture, xenografts, and genetically modified mice." (PMID 37880766, 2023). "Afterward, one study found that TRAIL/DR5 could interact with Rac1/PI3K/AKT and then induce proliferation and metastasis in KRAS‐mutated cells (NSCLC and PDAC tumor cells)." (PMID 37879960, 2023). "However, increased gene dose of the KRAS oncogene as well as the amplification or activation of MYC have been linked to tumor progression and metastasis." (PMID 37659057, 2023). "Therefore, we assessed the utility of INCERTS for identifying tumor-reactive TCRs directly from patients receiving a novel mutant KRAS peptide vaccine." (PMID 37776855, 2023). "Not all tumor cells depend on KRAS G12C for survival, as other alternative mutations, such as those involving AKT1, AKT2, PI3KCA, and PTEN, can activate the PI3K–AKT pathway." (PMID 37894382, 2023). "KRAS can regulate cell growth, differentiation and apoptosis, its mutations mainly occur at codons 12 and 13, and have been found approximately in 20-30% of NSCLC tumor samples." (PMID 36865554, 2023). "Alterations in the tumor immune microenvironment can also lead to primary drug resistance, such as the finding that tumor-associated macrophages can be recruited due to the effect of HDAC5 on chemokine, mediating SMAD4-dependent and KRAS-independent PDAC tumor growth." (PMID 36675641, 2023). "Immune evasion is a defining feature of KRAS-driven cancer, whereas KRAS produces immunosuppressive effects in tumour tissue by promoting macrophage M2 polarisation (suppressing-inflammatory phenotype), thereby creating a more hospitable TME ecological niche for cell proliferation and metastasis." (PMID 36936437, 2023). "The other important targets of miR-181d for tumor suppression are Bcl-2 and KRAS." (PMID 37371047, 2023). "This may indicate that UHRF1 is essential for the initial phases of KRAS-driven tumor growth, while the maintenance of spheroid growth may be less directly dependent on UHRF1 activity." (PMID 37407562, 2023). "With this in mind, our study aimed to evaluate the frequency of RAS mutations (including both KRAS and NRAS) and to investigate a possible association between these mutations and certain clinicopathological characteristics, as well as tumor localization, in a group of Bulgarian patients with mCRC." (PMID 37628934, 2023). "Notably, the silencing of UCP2 reduces glutaminolysis in both KRAS-mutant and KRAS wild-type cells, but only reduces the cell proliferation and tumour growth of KRAS-mutant cells." (PMID 36672360, 2023). "In addition, CM from DCA‐pretreated KRAS mutant tumor cells acquired the ability to sensitize T‐cells to AICD upon the addition of exogenous lactic acid." (PMID 36599679, 2023). "Additionally, mutant KRAS tumor status was shown to be an independent prognostic factor for PFS (91 days vs. 166 days, RAS-mutant vs. RAS-wild-type)." (PMID 36980565, 2023). "KRAS-mutant cancer cells govern immune responses through regulation of immune cell recruitment, activation, and differentiation, leading to enhancement of protumorigenic ability and promotion of tumor cell evasion." (PMID 36874015, 2023). "We developed a transient ex vivo patient-derived matched mucosa-tumor primary culture to assess whether anti-KRAS antibody can be internalized to bind and inactivate KRAS." (PMID 37051535, 2023).
tumor (continued). "Our current and previous studies identified that KRAS status represents an independent causative factor of tumor‐supporting immunoenvironment that is irrespective of KRAS mutation type, but positively correlates with mutated KRAS protein expression." (PMID 36599679, 2023). "Moreover, gene diagnosis has recently gained attention, and KRAS status is important in colorectal cancer treatment as a surrogate marker of tumor malignancy." (PMID 36983314, 2023). "We and others have reported that oncogenic KRAS, in the absence of further mutation, cooperates with inflammation to trigger large-scale chromatin remodeling events that promote tumor initiation." (PMID 37167403, 2023). "The KRAS mutational status and PD-L1 tumor expression by IHC did not seem to correlate with PD-L1 cmRNA Cy0-value." (PMID 38030703, 2023). "For example, fructose-bisphosphatase 1 could be inhibited by glycolysis, which leads to the dysfunction of NK cells and further tumor progression in KRAS-driven models of lung cancer." (PMID 37508545, 2023). "Moreover, targeted KRAS disruption mediated by HA-decorated CP/Ad−SS−GD/RNP nanocomplex was demonstrated to inhibit tumor growth and metastasis in colorectal cancer models." (PMID 38258073, 2023). "At present, use of EUS FNA KRAS mutation testing is not part of routine clinical practice, in part due to lack of standardization of sampling and often insufficient tumour tissue obtained via endoscopic biopsy." (PMID 37460806, 2023). "Some researches pointed out that it might because KRAS-mutant tumors had more tumor-infiltrating lymphocytes in the microenvironment and were almost always active." (PMID 37261523, 2023). "This analysis showed the persistence of the BRAF V600E mutation and the appearance of a novel KRAS G12C mutation that was absent in the initial tumor." (PMID 36967525, 2023). "Similarly, the resistance of tumours with KRAS mutations to anti-EGFR therapy are well documented, rendering tumours insensitive to this chemotherapeutic agent in many cases." (PMID 38136361, 2023). "Taken together, our findings suggest that KRAS mutation is not indicative of CRC tumor location, despite being proposed as part of the CIN carcinogenesis pathway." (PMID 36899966, 2023). "Furthermore, this work demonstrated that lactic acid production by tumor cells represented one of the several mechanisms by which mutant KRAS shapes tumor immunity." (PMID 36599679, 2023). "Finally in patient 3, amplifications of the CDK4 (13.6 copies) and KRAS (3.9 copies) genes were detected in the primary tumor." (PMID 37108696, 2023). "Moreover, in a different meta-analysis evaluating the circulating tumor DNA (ctDNA) in 106 advanced NSCLC patients, the KRAS mutations that were detected signified a worse OS (HR, 2.07; p = <0.01) for the patients treated with chemotherapy." (PMID 37373999, 2023). "Importantly, their development represents a major therapeutic advance that will likely extend to other KRAS G12C–mutant tumor types." (PMID 37384411, 2023). "However, the effectiveness of these cancer vaccines can be hindered by the oncogenic KRAS-induced reprogramming of the tumor microenvironment, leading to cancer cell immune evasion." (PMID 38069255, 2023). "We also show that this association of inflammation and CRC was seen irrespective of sex, CRC stage, grade, MSI status or KRAS mutation status of the tumor." (PMID 37296884, 2023). "Moreover, tunlametinib also showed potent anti-tumor effect in the BRAF/KRAS wild type xenograft model mice." (PMID 37808191, 2023). "Another source of resistance to KRAS targeted NSCLC therapies could be their unequal distribution across the tumor sites in a single patient." (PMID 37970206, 2023). "KRAS mutant cfDNA is detected in peritoneal fluids similar to tumor tissue in previous study." (PMID 37072801, 2023).
tumor (continued). "The roles of oncogenic KRAS in tumor immune evasion remain poorly understood." (PMID 36599679, 2023). "Interestingly, the anti-tumor response created during KRAS inhibition treatment only became durable when supplemented with a PD-1 inhibitor." (PMID 37925476, 2023). "However, KRAS were shown to localize largely at the inner plasma membrane resembling a net-like pattern in the KRAS p.Gly12Val (G12V) tumor." (PMID 37051535, 2023). "Metabolic reprogramming, the KRAS pathway, and relevant molecules may modulate the tumor, immune, and stromal components." (PMID 37187730, 2023). "These differential phenotypes of anti-KRAS antibody-treated tumor cells indicated that the internalized antibody is functional and could potentially be developed into novel antibody therapeutics for CRC." (PMID 37051535, 2023). "Finally, DEX as a single agent in a KRAS/LKB1 GEMM model resulted in significant overall tumor growth inhibition and complete tumor regression in one animal." (PMID 37035141, 2023). "A similar pattern was observed in tumor‐specific CTLs from KRAS wild‐type patients." (PMID 36599679, 2023). "Indeed, either genetic or pharmacologic inhibition of CXCR2 has been shown to reverse immunosuppression and hinder tumor progression in KRAS-mutant mouse models." (PMID 37581538, 2023). "KRAS mutations are present in 90% of PCs, and TILs can target mutant KRAS and inhibit tumor growth." (PMID 37529035, 2023). "Moreover, the effects of F.nucleatum and its metabolites on humans, especially the tumor initiation and progression-related pathways such as KRAS/BRAF, etc., should be investigated as well." (PMID 37630564, 2023). "The KRAS status is one of the surrogate markers for tumor biology." (PMID 36983314, 2023). "Finally, tumour epithelial AHCY expression was confirmed in APC and APC KRAS tumours and in human colon and CRC, with variation in expression between samples." (PMID 37580540, 2023). "Thus, KRAS can affect the biosynthesis of reduced NADPH, which is closely linked to redox balance and tumor growth." (PMID 36994237, 2023). "However, we found genomic alterations in KRAS, promoting the activation of the RAS pathway in this tumor, which has been suggested to be associated with luminal differentiation." (PMID 38098507, 2023). "Consequently, we suggest that AR can modulate the immune system by acting on the core targets EGFR, MAPK1 and KRAS, thus improving the tumor immune microenvironment." (PMID 37065830, 2023). "For example, CCR2 inhibitors such as PF-04136309 (ORR of 40% in PDAC trials) or epigenetic drugs such as HDAC inhibitors could be leveraged to impede KRAS-independent tumour progression." (PMID 36864508, 2023). "Pharmacological inhibition of oncogenic KRAS signaling induces rapid tumor resistance." (PMID 36928090, 2023). "In addition, KRAS signaling was also reported to remove defective mitochondria to also limit reactive oxygen species (ROS) and promote tumor growth." (PMID 36980608, 2023).
tumor (continued). "This may contribute to the reported downregulated tumor microenvironment for KRAS and the detection of responding T cells effective in adoptive therapy." (PMID 37215122, 2023). "Taken together, KRASG12C inhibitor-targeted immunotherapy or cotreatment of KRASG12C inhibitor with immunotherapy represents new directions in tackling drug resistance to KRASG12C inhibitors through remodeling the immunosuppressive tumor microenvironment driven by KRAS mutants." (PMID 37221195, 2023). "A major predictive genetic biomarker is wild-type vs. mutant KRAS tumor status." (PMID 36980565, 2023). "Likewise, inactivation of wild-type KRAS was expected to increase tumor number and/or growth in the KRAS G12C and KRAS G12D contexts, as wild-type KRAS suppresses oncogenic KRAS33." (PMID 37828026, 2023). "Therefore, compared with control tumor spheroids, LKB1−/− KRAS-driven tumor spheroids exhibited low levels of immune cell infiltration." (PMID 38106674, 2023). "A tumor-agnostic analysis across the 25 TCGA tumor types did not identify a c-Score expression difference between KRAS wild-type versus mutated tumors (Wilcoxon rank-sum)." (PMID 37558751, 2023). "In each of these three patients, one, but not all, of the independent tumours forming the collision tumour harboured a targetable KRAS G12C driver mutation." (PMID 37046096, 2023). "Crucially, as a consequence of this EGFR feedback model, combining oncogenic RAS inhibitors with clinically used EGFR inhibitors could lead to increased tumor regression and extended survival in patients with KRAS-mutant CRC." (PMID 37020035, 2023). "Additionally, a new G12C inhibitor that targets active RAS-GTP is being developed and has shown effectiveness against KRAS-G12C tumor cells with resistance to previous inhibitors." (PMID 37662925, 2023). "Most BA/CMPT cases have been reported from Japan and other Asian countries and may involve genetic mutations of BRAF, EGFR, KRAS, HRAS, and ALK; thus, the tumor is viewed as an oncological disease." (PMID 39517003, 2023). "When considering cancer immunity, oncogenic KRAS may promote immunosuppressive tumor microenvironments." (PMID 37558751, 2023). "PLCγ1 promotes tumor cell proliferation in KRAS-mutant LC cells, suggesting that PLCγ1 is a novel interactor of the EphA2 RTK in LC cells and that the EphA2–PLCγ1 signaling axis could be a promising therapeutic strategy for treating LC." (PMID 37370855, 2023). "In contrast, reduced copper bioavailability inhibits the proliferation of KRAS mutant tumor cells." (PMID 37427098, 2023). "KRAS inhibition in immunocompetent mouse tumor models reversed this phenotype and resulted in an increased M1/M2 macrophage polarization ratio as well as increased tumor-infiltrating CD4+ and CD8+ T cells." (PMID 37444422, 2023). "An oncogenic KRAS sets the metabolic changes by hyperactivation of growth factor signaling that ultimately leads to increase of a cellular glycolytic flux facilitating tumor growth." (PMID 36359850, 2022). "In addition, KRAS-independent, but AMPK-dependent, macropinocytosis in cancer-associated fibroblasts is necessary for PDAC tumor growth." (PMID 35287706, 2022).
tumor (continued). "Hence, with the help of LCM on healthy pancreatic tissue and tumor tissues, the expression study of gastrin unveiled its possible role in activating KRAS in PC." (PMID 36498893, 2022). "In addition, iRhom2, as a key binding protein for ADAM17, further promotes KRAS-induced tumor cell growth by modulating the release of ERBB ligands." (PMID 36466812, 2022). "This is consistent with the previously reported study concerning inhibition of tumor growth by Furin silencing in KRAS or BRAF mutated cells but not in wild-type KRAS and BRAF cells." (PMID 35267511, 2022). "Tetrac also inhibits tumor growth in the HCT-116 (KRAS MT CRC) mouse xenograft model." (PMID 36005485, 2022). "Because tumor variations may be a factor for survival, we included KRAS and PIK3CA variation status in 461 patients with available data." (PMID 36239938, 2022). "Besides the establishment of a tumor-promoting inflammation in the TME through a wide variety of mechanisms, KRAS itself has also been associated with immunomodulatory and immune escape effects." (PMID 35965494, 2022). "EMT transformation is a known adaptive resistance mechanism both in EGFR and KRAS driven tumours." (PMID 36284306, 2022). "In COAD, the formation of KRAS-induced tumor and the generation of drug resistance are related to copper metabolism, and the use of copper chelating agent can inhibit the growth of tumor cells." (PMID 36203457, 2022). "Interestingly, we found that tumors with high-grade tumor budding were more likely to be microsatellite stable (MSS) (P=0.005) and harbor more KRAS mutations (P=0.02)." (PMID 35096426, 2022). "The baseline characteristics, including sex, sidedness, tumor grade, histology, stage at diagnosis, KRAS/NRAS mutation status, and MSI status, were not different between the two groups." (PMID 35625987, 2022). "This compound was shown to inhibit oncogenic KRAS signaling selectively in tumor cells." (PMID 36531078, 2022). "Therefore, since OIS is one of the earliest tumor suppressor mechanisms that is triggered in response to activation of the MEK–ERK pathway by oncogenic mutations in KRAS or BRAF, founder cells have to first overcome OIS for tumor initiation to occur." (PMID 35975243, 2022). "Detecting the PDAC markers by PCR aimed at detecting a common gene such KRAS, performing tumor formation assays, and performing targeted sequencing to identify tumor cells at the start may resolve this situation." (PMID 36687406, 2022). "Particularly, KRAS G12D had significantly higher tumor SOX9 than KRAS WT." (PMID 34919787, 2022). "Interestingly, the hypomethylation of KRAS is decreased in LUSC, BRCA, ESCA, and LIHC, even though we found a significant upregulation of KRAS in these tumors, suggesting a complex tumor microenvironment, and further mechanisms in this manner are needed." (PMID 35563733, 2022).